AFP (alpha fetoprotein)
Diseases named in the same sentence as AFP in open-access papers (continued):
Sharing a sentence is not in itself a finding about the gene and the disease.
obstructive jaundice (3 papers, 2021 to 2025). A finding indicating increased bilirubin levels in the blood and urine, due to intrahepatic or extrahepatic obstruction of the biliary system. "Except for healthy individuals, the positive rate of serum PIVKA‐II was significantly higher than that of AFP among the other three groups, and patients with obstructive jaundice had the highest positive rate of PIVKA‐II." (PMID 41230775, 2025). "This study aimed to investigate the distribution and positive rates of serum PIVKA‐II and AFP in patients with obstructive jaundice or sepsis, and to explore their relationships with laboratory tests, particularly coagulation function indexes." (PMID 41230775, 2025). "Therefore, we conducted a study involving patients with obstructive jaundice or sepsis to investigate the distribution and positive rates of PIVKA‐II and AFP and their relationships with laboratory tests." (PMID 41230775, 2025). "However, positive correlations were observed between AFP and ALT, AST, and bile acids (p < 0.001, p = 0.006, and p = 0.022, respectively) in obstructive jaundice, and between AFP and WBC, neutrophils, and CRP (p < 0.001, p = 0.001, and p = 0.005, respectively) in sepsis." (PMID 41230775, 2025).
ovarian clear cell cancer (3 papers, 2018 to 2025). An invasive malignant neoplasm that arises from the ovary and is characterized by a predominance of clear and hobnail malignant epithelial cells. "The expression of CN positively correlated with the serum cancer antigen 125 (CA125) level in ovarian clear-cell carcinoma and the serum alpha-fetoprotein (AFP) level in papillary serous cystadenocarcinoma." (PMID 31399054, 2019). "Taken together, the combination of morphological and immunohistochemical findings confirmed the diagnosis of AFP-producing ovarian clear cell carcinoma with fetal gut differentiation." (PMID 29933751, 2018). "Based on univariate analysis, the CN expression positively correlated with pathological stage in ovarian serous carcinoma, with serum CA125 level in ovarian clear-cell carcinoma, and with serum AFP level in ovarian papillary serous cystadenocarcinoma (p < 0.05)." (PMID 31399054, 2019). "Lastly, ovarian clear cell carcinoma (CCC), more common in postmenopausal women, usually presents as a pelvic mass with mild AFP elevation." (PMID 40919162, 2025).
Ovarian cyst (3 papers, 2020 to 2024). The presence of one or more cysts of the ovary. "Potentially, assessment of the AFP level can contribute to the earlier detection of fetal ovarian cysts and increase the chances of preserving ovarian function." (PMID 38379864, 2024). "(2021), which showed that the serum AFP level was elevated among newborns with ovarian cysts." (PMID 38379864, 2024).
ovarian endodermal sinus tumor (3 papers, 2023 to 2024). "AFP is a specific marker of ovarian endodermal sinus tumor and can also be used in diagnosis." (PMID 38704534, 2024). "High postoperative AFP levels were associated with worse OS (OR = 0.16, 95% CI: 0.05–0.48) and RFS (OR = 0.18, 95% CI: 0.08–0.43) compared to low postoperative AFP levels in ovarian yolk sac tumor (OYST) patients." (PMID 37686577, 2023).
ovarian teratoma (3 papers, 2013 to 2026). A non-seminomatous germ cell tumor arising from the ovary. "It has been previously reported that 7.5% of ovarian teratomas are positive for the expression of AFP and 22.6% for CA125." (PMID 24273602, 2013). "AFP monitoring is not recommended in case of completely resected ovarian teratomas without preoperatively elevated tumor markers." (PMID 30165903, 2018). "Therefore, AFP and CA125 are not the specific criterion for predicting ovarian teratomas." (PMID 24273602, 2013).
placenta accreta (3 papers, 2012 to 2022). The clinical condition in which any part of the placenta invades and is inseparable from the uterine wall. "Other than the imaging methods, elevated biochemical markers in maternal serum such as elevated levels of alpha fetoprotein and human chorionic gonadotropin within the triple screening test have been reported to be associated with an increased risk of placenta accreta." (PMID 22645616, 2012). "Recent studies have shown that patients with placenta accreta or percreta have high serum alpha-fetoprotein and serum hCG levels." (PMID 26480940, 2015). "The serum AFP, β-hCG and CK levels followed the order of placenta percreta group > placenta increta group > placenta accreta group > non-PA group." (PMID 36581918, 2022).
Pleural effusion (3 papers, 2005 to 2025). The presence of an excessive amount of fluid in the pleural cavity. "Alpha-fetoprotein (AFP), beta-human chorionic gonadotropin (beta-hCG), carbohydrate antigen 19-9 (CA 19-9), and fibrinogen values were significantly elevated, although AFP and beta-hCG showed a slight decrease following pleural effusion evacuation." (PMID 41384202, 2025). "In spite of that, the context, the rising AFP, and the otherwise unexplained pleural effusion lead to the conclusion of an HCC recurrence, with a time to progression after surgery of 19 months." (PMID 26166099, 2015). "In December 2013, he presented a pleural effusion and increased AFP serum levels." (PMID 26166099, 2015).
pneumonia (3 papers, 2019 to 2026). An acute, acute and chronic, or chronic inflammation focally or diffusely affecting the lung parenchyma, caused by an infection in one or both of the lungs (by bacteria, viruses, fungi, or mycoplasma.). "This case underscores that HAL may mimic nonresolving pneumonia and that normal AFP does not exclude the diagnosis; early biopsy and a targeted immunohistochemical panel are essential for timely recognition of this lethal entity." (PMID 42100591, 2026).
schwannoma (3 papers, 2013 to 2022). A benign, usually encapsulated slow growing tumor composed of Schwann cells. "Tumor markers including AFP and CA125 contributed to the differential diagnosis of gynecological tumors versus schwannomas." (PMID 31626091, 2019).
Sepsis (3 papers, 2014 to 2025). Sepsis is defined as life-threatening organ dysfunction caused by a dysregulated host response to infection. "Both baseline age and AFP levels were associated with extrahepatic mortality, which was mainly caused by sepsis." (PMID 31110209, 2019). "Similarly, the AFP levels showed significant differences among all groups except for sepsis patients and healthy controls (p < 0.001)." (PMID 41230775, 2025). "The receiver operating characteristic (ROC) curve was used to determine the specificity and sensitivity of PIVKA‐II and AFP in diagnosing HCC under the interference of obstructive jaundice and sepsis." (PMID 41230775, 2025). "However, in the presence of sepsis and obstructive jaundice, the specificity, YI, positive likelihood ratio (+LR), and positive predictive value (PPV) of PIVKA‐II were inferior to AFP." (PMID 41230775, 2025). "Furthermore, serum PIVKA‐II was positively associated with AFP in patients with primary HCC, but no such association was observed in patients with obstructive jaundice and sepsis." (PMID 41230775, 2025).
small cell carcinoma (3 papers, 2011 to 2023). A neuroendocrine carcinoma composed of small malignant cells which are often said to resemble "oat cells" under the microscope. "We encountered a patient with an AFP-positive small cell carcinoma and report here the clinical course." (PMID 37721573, 2023). "This discrepancy suggested a histologic type unresponsive to or cancer cells potentially resistant to chemotherapy, thus a surgical re-biopsy was performed and histological findings revealed AFP-positive small cell carcinoma." (PMID 37721573, 2023). "Rare small cell neuroendocrine carcinoma (SCNEC) cases showed alpha fetoprotein (AFP) expression in the endometrium." (PMID 34805530, 2021). "Surprisingly, histological findings in our patient showed small cell carcinoma with immunohistochemical positivity for AFP, which to the best of our knowledge has never been described occurring in the thymus." (PMID 37721573, 2023). "An AFP-positive small cell carcinoma is an uncommon tumor with no standard treatment strategy." (PMID 37721573, 2023).
testicular teratoma (3 papers, 2023 to 2024). "Typically, AFP levels remain within the normal range in prepubertal testicular teratomas, though they may occasionally be elevated in cases involving large tumors or very young children." (PMID 39606696, 2024).
Acute hepatic failure (2 papers, 2018 to 2025). Hepatic failure refers to the inability of the liver to perform its normal synthetic and metabolic functions, which can result in coagulopathy and alteration in the mental status of a previously healthy individual. "In most cases, there is a substantial increase in the tumor biomarker alpha-fetoprotein (AFP) and mainly acute hepatic failure." (PMID 40332516, 2025). "However, limited studies demonstrated a correlation between AFP levels and the outcomes of patients with ACLF, especially patients with acute hepatic failure based on chronic HBV infection." (PMID 29854714, 2018).
acute-on-chronic liver failure (2 papers, 2018 to 2024). Acute-on-chronic liver failure (ACLF) is an extreme condition during the natural history of chronic HBV infection, with a relatively high short-term mortality. "AFP could be a useful marker to predict outcomes of acute-on-chronic liver failure." (PMID 29854714, 2018).
adenocarcinoma of the cervix (2 papers, 1981 to 2021). "There was also a significant correlation between AFP and hCG levels in adenocarcinoma of the cervix (r = 0.53, P less than 0.05)." (PMID 6169360, 1981).
adrenal tumor (2 papers, 2019 to 2023). "Immunohistochemical staining revealed that both HCC cells and adrenal tumor cells were positive for HCC markers Glypican-3 and alpha-fetoprotein." (PMID 31696344, 2019). "AFP is partially expressed in the HCC and only focally in the adrenal tumor." (PMID 31696344, 2019).
alcoholic hepatitis (2 papers, 2020 to 2023). Acute hepatitis resulting from ingestion of alcohol. "Patients from the whole set were stratified by different infection type (HBV, HCV, alcoholic hepatitis), age (≥60 or <60 years), TNM stages (stage I and II or stage III and IV), and AFP level (>300 or ≤ 300)." (PMID 33505990, 2020).
aneuploidy (2 papers, 2021 to 2022). Chromosomal disorder consisting of the presence a chromosomal abnormality in which there is an addition or loss of chromosomes within a set. "In conclusion, based on AFP, free β-hCG, and DD in the second trimester of pregnancy, fetal aneuploidy screening and maternal HDP prediction can be performed simultaneously." (PMID 33653375, 2021). "The most common biomarkers identified and analyzed were those measured during routine first and second trimester screening for aneuploidy, including pregnancy associated plasma protein A (PAPP-A), human chorionic gonadotropin (hCG), alpha fetoprotein (AFP), and estriol." (PMID 35377904, 2022).
Barrett esophagus (2 papers, 2007 to 2021). Esophageal lesion lined with columnar metaplastic epithelium which is flat or villiform. "Various single case reports of alpha-fetoprotein (AFP) producing esophageal adenocarcinomas leading to liver metastases are described in the literature, but have not been described in large cohorts." (PMID 34503162, 2021).
benign breast disease (2 papers, 2021 to 2023). "In the subgroup of patients with benign breast diseases, very good correlations were found for CEA (R = 0.89), CA 15-3 (R = 0.84), CA 125 (R = 0.87), and AFP (R = 0.94), respectively, while the correlations were worse for CA 19-9 (R = 0.52)." (PMID 37835844, 2023).
benign testicular tumors (2 papers, 2019 to 2023). "As a rare kind of benign tumor in the testis, TART has to be diagnosed very carefully, and a reference to typical CAH symptoms, AFP, HCG, and hormonal levels and a positive finding in adrenal glands can be of help to increase diagnostic accuracy." (PMID 31694673, 2019).
beta thalassemia (2 papers, 2020 to 2024). Beta-thalassemia (BT) is characterized by deficiency (Beta+) or absence (Beta0) of synthesis of the beta globin chains of hemoglobin (Hb). "For maternal serological indicators, Tongprasert F and other researchers have identified maternal serum alpha fetoprotein (AFP), placental like growth factor (PlGF), inhibin-A, and other biomarkers as potentially effective in predicting fetal α-thalassemia major during the second trimester." (PMID 39726529, 2024). "Also in beta-thalassemia patients at risk of HCC, surveillance should be performed by abdominal US and AFP serum determination every 6 moths." (PMID 32746786, 2020). "Although AFP is increased > 400 ng/ml (the value considered diagnostic for HCC) in only 20–25% of patients with HCC, either with beta-thalassemia or without, it allows to identify patients at risk when baseline values are > 20 ng/ml, or if they increase over time." (PMID 32746786, 2020).
biliary tract cancer (2 papers, 2014 to 2023). "Current guidelines recommend abdominal ultrasonography (USG) and alpha-fetoprotein (AFP) monitoring for HCC screening in high-risk groups, and abdominal USG, magnetic resonance imaging (MRI), and magnetic resonance cholangiopancreatography (MRCP) monitoring for biliary tract cancer." (PMID 37568696, 2023). "However, the level of AFP in certain patients with HCC and those of biliary tract cancers does not become elevated." (PMID 25364458, 2014).
brain tumor (2 papers, 2014 to 2021). "This is confirmed by the positive correlation between elevated levels of hCG or AFP and the diagnosis of brain tumors." (PMID 34829327, 2021). "High alpha-fetoprotein levels (539 ng/ml) were evident and magnetic resonance imaging suggested a 45-mm single brain tumor in the right parietal lobe, for which surgery was performed." (PMID 25444462, 2014).
Budd-Chiari syndrome (2 papers, 2025). "Alpha-fetoprotein was negative, making malignant and infectious causes of HA less likely in our case, and abdominal ultrasound showed potent hepatic vasculature, ruling out Budd-Chiari syndrome." (PMID 40827155, 2025).
celiac disease (2 papers, 2022 to 2025). An autoimmune genetic disorder with an unknown pattern of inheritance that primarily affects the digestive tract. "Additional diagnostic tests, including screening for immune-mediated ataxias, antibodies associated with celiac disease, oncological markers, alpha-fetoprotein, vitamin E, and acanthocytes, all yielded normal results." (PMID 41153398, 2025).
chorioangiomas (2 papers, 2013 to 2025). "Maternal serum alpha-fetoprotein (AFP) elevation is thought to be associated with placental diseases, including chorioangiomas and mesenchymal dysplasia." (PMID 40771393, 2025). "Elevated maternal serum AFP levels during the second trimester screening may also alarm about the possibility of the placental angioma." (PMID 24251055, 2013).
chronic liver failure (2 papers, 2018 to 2024). Liver failure that develops slowly and gradually for some time, possibly for years, often as the result of cirrhosis, or malnutrition. "Indicators of chronic liver failure were observed, with mildly low albumin level 36 g/L (normal 37–56) and a normal serum alpha‐fetoprotein (AFP) level." (PMID 39512434, 2024).
colorectal tumor (2 papers, 2021 to 2026). "Colon and rectal adenocarcinoma with enteroblastic differentiation (CAED) is the most common type of AFP-producing colorectal tumor." (PMID 41589237, 2026).
congenital adrenal hyperplasia (2 papers, 2023 to 2024). Congenital adrenal hyperplasia (CAH) is an inherited endocrine disorder caused by a steroidogenic enzyme deficiency that is characterized by adrenal insufficiency and variable degrees of hyper or hypo androgyny manifestations, depending of the type and the severity of the disease. "CAH: congenital adrenal hyperplasia; TART: testicular adrenal rest tumor; AFP: alpha-fetoprotein; beta HCG: beta human chorionic gonadotropin." (PMID 39050357, 2024).
cryptogenic cirrhosis (2 papers, 2020 to 2023). "Interestingly, PLSec-AFP performed significantly better in the subgroup of patients with NAFLD/cryptogenic cirrhosis (with an aHR of 11.9)." (PMID 37627890, 2023). "Patient H199 is a 64-year-old male with cryptogenic cirrhosis and a 9.0 cm segment 2–3 AFP-nonproducing lesion who underwent a left hepatectomy." (PMID 32637655, 2020).
Ehrlich tumor (2 papers, 2019 to 2023).
encephalitis (2 papers, 2018 to 2023). An acute inflammatory process affecting the brain parenchyma. "Nine patients also presented AFP (along with encephalitis or meningoencephalitis)." (PMID 37515168, 2023).
Fulminant hepatic failure (2 papers, 2010 to 2012). "Sixty-four patients with fulminant hepatic failure were examined regarding their serum alpha-fetoprotein (AFP) levels." (PMID 22973230, 2012).
galactosemia (2 papers, 2021 to 2022). "Case reports have linked elevated AFP levels to other metabolic diseases such as citrullinemia type-2, twinkle variants, galactosemia, bile acid synthesis defects and gestational alloimmune liver disease (GALD, formerly termed neonatal hemochromatosis)." (PMID 35455589, 2022).
gall bladder tumor (2 papers, 2009 to 2025). "A previous case reported an AFP-producing gallbladder carcinosarcoma with a level of 1,495 ng/mL, while the level in our case was even higher (2,786 μg/L), potentially associated with hepatic invasion by the gallbladder tumor." (PMID 41357596, 2025). "He received transcatheter arterial chemoembolization, and was diagnosed to have an alpha-fetoprotein producing gall bladder tumor with intraluminal growth." (PMID 19830175, 2009).
gastric teratoma (2 papers, 2024 to 2025). A mature or immature teratoma that arises from the stomach. "The gastric teratoma case with the yolk sac component had a raised baseline AFP value, otherwise baseline values of AFP, b hCG, and LDH were within normal limits according to age in rest of the cases." (PMID 39686951, 2024). "Given the complete surgical excision and the rarity of malignant behavior in gastric teratomas, no adjuvant chemotherapy was administered; however, the patient was scheduled for close surveillance with periodic abdominal ultrasounds and serial serum alpha-fetoprotein (AFP) levels." (PMID 40336679, 2025).
gastric varices (2 papers, 2021 to 2025). "In the multivariable analysis, older age, presence of oesophageal or gastric varices, AFP > 200 ng/mL and a more advanced BCLC stage were independent predictors of mortality, with HRs increasing progressively for stage from A to D." (PMID 41250947, 2025).
gynecological cancers (2 papers, 2023 to 2025). "Emerging evidence indicates that carcinoembryonic antigen (CEA), alpha-fetoprotein (AFP), and human chorionic gonadotropin (HCG) are established biochemical markers in plasma and tumors of patients with gynecological malignant tumors, according to emerging evidence." (PMID 37594950, 2023).
hepatic lymphoma (2 papers, 2009 to 2014). "Primary hepatic lymphoma is a rare entity that should be considered in any patient with liver mass or liver infiltration, especially with normal levels of alpha-fetoprotein and CEA." (PMID 23686662, 2014). "Primary hepatic lymphoma should be considered in the differential diagnosis in a patient with space-occupying liver lesions and normal levels of alpha-fetoprotein and cea." (PMID 19672429, 2009). "The case demonstrates that primary hepatic lymphoma should be considered in the differential diagnosis of space-occupying liver lesions in presence of normal levels of alpha-fetoprotein and carcinoembryonic antigen." (PMID 19672429, 2009).